CDK5 (cyclin dependent kinase 5)
Diseases named in the same sentence as CDK5 in open-access papers (continued):
Sharing a sentence is not in itself a finding about the gene and the disease.
gastric cancer (continued). "Nevertheless, similar to CDK5, PP2A is also downregulated in gastric cancer, which is associated with poorer overall survival." (PMID 37993880, 2023). "Taken together, our in vitro and in vivo findings suggest that CDK5 significantly promoted apoptosis and sensitized gastric cancer cells to oxaliplatin." (PMID 37990321, 2023). "Our findings suggest CDK5 as a potential prognostic factor and molecular biomarker for chemotherapeutic decisions in gastric cancer." (PMID 37990321, 2023). "We demonstrate that CDK5 promotes apoptosis in gastric cancer cells by directly binding to DP1 and subsequently activating E2F1 signaling." (PMID 37990321, 2023). "In this study, we analyzed differentially expressed genes (DEGs) across established apoptotic phenotypes and identified CDK5 as a proapoptotic gene in gastric cancer." (PMID 37990321, 2023). "Although CDK5 has been reported as an oncogenic protein in various cancer types, the opposite results have also been reported in gastric cancer." (PMID 34207842, 2021). "In contrast with all these findings, CDK5 was postulated by others to act as a tumour suppressor in gastric cancers." (PMID 31910742, 2020). "Low expression of CDK5 displays poor patient survival, while nuclear CDK5 accumulation prevents the proliferation and metastasis of gastric cancer cells." (PMID 33396266, 2020). "The authors reported that low levels of CDK5 in gastric carcinomas correlated with poor patient survival and the presence of metastases, while high CDK5 levels conferred an improved prognosis." (PMID 31910742, 2020). "NS-0011, which inhibits the translocation of Cdk5 from nucleus to cytoplasm, can suppress the proliferation and xenograft tumorigenesis of gastric cancer cells." (PMID 28288624, 2017). "For example, in human gastric cancer tissues, the mRNA level and protein level of Cdk5 and p35 are both significantly reduced, and the down-regulation is linked with poorer prognoses." (PMID 28288624, 2017). "There are several known non-ERBB regulators of ERBB3, such as MET, BRK, EBP-1 and CDK5, in gastric cancer." (PMID 26942872, 2016). "Furthermore, the expression levels of Tau, a Cdk5 substrate, have been proposed as a predictive biomarker for paclitaxel response in both breast and gastric cancers, with low Tau expression correlating with better outcomes." (PMID 41369365, 2025). "Interestingly, oxaliplatin treatment increased the levels of cleaved PARP and caspase 3 and promoted the expression of CDK5 in gastric cancer cell lines." (PMID 37990321, 2023). "CDK5 depletion contributes to poor prognosis and chemoresistance in patients with gastric cancer." (PMID 37990321, 2023). "To investigate whether CDK5 exerts its tumor-suppressive function in gastric cancer by activating apoptosis in tumor cells, we performed Annexin V/PI staining in the AGS and MKN45 cell lines to detect apoptosis." (PMID 37990321, 2023). "Our findings suggest that CDK5 may serve as a biomarker for the prognosis and therapeutic decisions in patients with gastric cancer." (PMID 37990321, 2023). "Uniquely in gastric cancer, CDK5 acts as a tumor suppressor." (PMID 37993880, 2023). "Importantly, in gastric cancer, CDK5 levels are much lower than those in normal gastric tissues, which correlates with decreased patient survival and metastases." (PMID 37993880, 2023). "Importantly, ectopic expression of CDK5 in gastric cancer cells decreased tumour cell proliferation in vitro and in vivo in xenografts." (PMID 31910742, 2020). "Moreover, the nuclear accumulation or localization of CDK5 is also reduced in gastric cancer cells." (PMID 36769170, 2023). "Thus, our results suggest that CDK5 is a proapoptotic gene in gastric cancer." (PMID 37990321, 2023). "The exact function of CDK5 in gastric cancer remains largely unknown." (PMID 37990321, 2023). "However, some authors argued that CDK5 acts as a tumour suppressor in gastric cancer." (PMID 33396266, 2020).
gastric cancer (continued). "However, decreased expression of CDK5 was detected in gastric cancer." (PMID 26860827, 2016). "However, downregulated expression of CDK5 was observed in gastric cancer." (PMID 26860827, 2016). "CDK5 interacts with PP2A, another protein downregulated in gastric cancer, and correlates with worse overall survival." (PMID 39800748, 2025). "However, the molecular mechanisms by which nuclear CDK5 acts as a tumor suppressor are largely unknown in gastric cancer, except for one study that showed that nuclear CDK5 upregulates the levels of the CDK inhibitor p16INK4a, which contributes to cell cycle arrest." (PMID 37993880, 2023). "Our findings reveal that CDK5 promotes cell apoptosis by stabilizing DP1 and activating E2F1 signaling, suggesting its potential role in the prognosis and therapeutic decisions for patients with gastric cancer." (PMID 37990321, 2023). "Cellular experiments show a lack of Cdk5 in nucleus in different gastric cancer cell lines, but presence of Cdk5 in both the nucleus and cytoplasm in normal gastric epithelial cell line." (PMID 28288624, 2017). "Notably, this oncogenic function is not universal, as Cdk5 exhibits its duality even within the context of cancer; it acts as a tumor suppressor in gastric cancer upon nuclear localization." (PMID 41369365, 2025). "In addition, we tested CDK5 expression using IHC staining in TMAs with 340 evaluable gastric cancer tissues and 97 evaluable adjacent nontumor tissues." (PMID 37990321, 2023). "Unlike most other cancers, CDK5 acts as a tumor suppressor in gastric cancer." (PMID 37993880, 2023).
Huntington disease (18 papers, 2015 to 2024). Huntington disease (HD) is a rare neurodegenerative disorder of the central nervous system characterized by unwanted choreatic movements, behavioral and psychiatric disturbances and dementia. "These include angiogenesis, cell migration, inflammation and metabolism, while deregulated CDK5 signaling is implicated in neurodegeneration and Huntington's disease, as well as cancer." (PMID 29535807, 2018). "However, cleavage of p35 by calpains to p25 leads to aberrant activation of CDK5 and has been associated with neurodegeneration in PD and Alzheimer's and Huntington's diseases." (PMID 31911436, 2020). "For that purpose, we utilized a 3-NP-induced model designed to simulate the early stages of Huntington’s disease and assessed both the initial damage induced by 3-NP and the role of Cdk5 in disrupting striatal synaptic plasticity." (PMID 39569019, 2024). "Cdk5-dependent phosphorylation of acn-S437 in nil1 animals elevates neuronal autophagy and reduces the accumulation of polyQ proteins in a Drosophila Huntington’s disease model." (PMID 35037620, 2022). "Another study showed Cdk5 in the nucleus accumbens as a critical contributor to depressive-like behaviors in Huntington's disease mouse models." (PMID 34035826, 2021). "Furthermore, existing literature indicates an increase in Cdk5 expression or activation in the striatum of animal models exhibiting Huntington’s disease (HD), where synaptic plasticity alterations have been documented." (PMID 39569019, 2024). "Our results reveal that, in a pharmacological model induced by 3-NP treatment, which simulates earlier stages of Huntington’s disease (HD), Cdk5 may play a role in attenuating signaling pathways, influencing neurons to enhance their activity." (PMID 39569019, 2024). "However, Cdk5 activity becomes deregulated in several neurological disorders, such as Alzheimer’s disease, Parkinson’s disease, and Huntington’s disease, which leads to neurotoxicity." (PMID 39596381, 2024). "Indeed, inhibition of CDK5 activity abrogates the increase in mitochondrial fission by inhibiting DRP1 activity in Huntington’s disease model and NMDA-induced neuronal loss." (PMID 28919853, 2017).
ischemia (16 papers, 2010 to 2024). A hypoperfusion of the BLOOD through an organ or tissue caused by a PATHOLOGIC CONSTRICTION or obstruction of its BLOOD VESSELS, or an absence of BLOOD CIRCULATION. "To summarize, CaMKII, PKC, and Cdk5 exhibit reduced kinase activity at the PSD after ischemia, which can be reversed by the removal of ubiquitin." (PMID 38480905, 2024). "Conditional knockout of Cdk5 activity has been shown to provide neuroprotection from ischemia and experimental models of brain injury." (PMID 36854738, 2023). "Conditional knockout of Cdk5 is neuroprotective in models of ischemia and experimental brain injury." (PMID 36854738, 2023). "In both focal and global ischemia, elevated phosphorylation of Prx2 at Thr89 and ROS accumulation were found due to upregulated cytoplasmic Cdk5 activity." (PMID 36438186, 2022). "Inhibition of Cdk5 using Roscovitine protects axon function only when applied during ischemia, mainly acting on oligodendrocytes and axons." (PMID 35911974, 2022). "In vivo, in rat 2VO model, transplantation of CDK5-knockdown (KD) astrocytes into the somatosensory cortex after ischemia rescued motor and neurological impairment the first week compared to transplantation of WT-astrocytes." (PMID 33429982, 2021). "In a rat focal ischemia model induced by endothelin-1 injection, CDK5 activity increased at 3, 12, and 24 h after ischemia in both cells’ cytoplasm and nuclei." (PMID 33429982, 2021). "To date, numerous studies have supported the role of Cdk5 in several pathological phenotypes including cancer, neurodegenerative diseases, and ischemia." (PMID 31137734, 2019). "In the case of CDK5, we have designed a shRNAmiR that, in a cerebral ischemia model, resulted in neurologic and motor improvement during the first week after ischemia." (PMID 28420961, 2017). "Following ischemia, CDK5 is involved in astrocyte reactivity." (PMID 33429982, 2021). "Additionally, CDK5 RNAi (RNA interference) prevented dysfunctions in learning, memory and reversal learning at a month after ischemia." (PMID 28420961, 2017). "In this study, the enhanced p-NR2AS1232 expression after ischemia was inhibited by TFP5, which indicated specific CDK5 inhibitor TFP5 protecting the brain cells after ischemia may be resulted from the inhibition on NR2A-mediated excitotoxicity." (PMID 28045138, 2017). "It was hypothesized that the Cdk5-mediated activation of NMDA receptors is an underlying cause of ischemia-induced damage in CA1 pyramidal neurons and expression of a Cdk5 dominant negative mutant protected neurons from such damage." (PMID 25364642, 2012). "CDK5 has been identified as a putative therapeutic target in ischemia." (PMID 20711428, 2010). "Cdk5 mediates serine phosphorylation of Tau S202/205 and Crmp2 S522 at the PSD, which was reduced after ischemia, accompanied by a decrease in Cdk5 activity." (PMID 38480905, 2024). "On the other hand, during ischemia, CK2 signaling mediates injury to glial cells and impairs axon function either directly and/or through Cdk5 and PTEN/AKT/GSK3β signaling regulation of downstream effectors." (PMID 35911974, 2022). "Nuclear Cdk5 contributes to neuronal death following focal ischemia but not global ischemia by phosphorylating MEF2." (PMID 36438186, 2022). "Cdk5 was shown to inhibit HDAC1 function and induce double-strand DNA breaks and cell cycle reentry, resulting in neurodegeneration and neurologic defects following ischemia." (PMID 36438186, 2022). "Although it has been postulated that pilot inhibitors of Cdk5, such as enantiomers of roscovitine, display improved BBB permeability and functional protection following ischemia, Cdk5 site-directed decreases in phosphorylation stoichiometry have not been clearly shown." (PMID 35645825, 2022). "CDK5 has been demonstrated to phosphorylate NMDA receptors, which in turn results in calcium overload and excitotoxicity, thereby inducing cell death following ischemia in hippocampal neurons." (PMID 31595208, 2019).
ischemia (continued). "However, Cdk5 inhibition fails to exert post-ischemic protection to axon function, implying that Cdk5 signaling is important to alleviate oxidative injury specifically during ischemia." (PMID 35911974, 2022). "CDK5 activation and CDK5-Tyr15 phosphorylation were observed in the hippocampus of the rats that had been subjected to middle cerebral artery occlusion, both of which were reversed by pretreatment with zinc chelator; while p35 cleavage and calpain activation in ischemia were not reversed." (PMID 30158515, 2018). "The results show that CDK5 activation was accompanied with Tyr15 phosphorylation in the hippocampus of the rats that had been subjected to MCAO, both of which were reversed by pretreatment with zinc chelator; whereas p35 cleavage and calpain activation in ischemia were not reversed." (PMID 30158515, 2018).
schizophrenia (16 papers, 2010 to 2025). A major psychotic disorder characterized by abnormalities in the perception or expression of reality. "The activity of PV or Cdk5 is deregulated in various brain disorders including AD and schizophrenia, while little is known about their relation." (PMID 35008611, 2021). "Moreover, multiple reports reveal an association between significantly decrease in CDK5 and CRMP2 and some neuropsychiatric disorders such as schizophrenia, ADHD and bipolar." (PMID 41255384, 2025). "Therefore, it is of interest to further characterize the physiological functions of the Cdk5-dependent regulation of Rap1 signalling via RapGEF2 and RapGEF6 in psychiatric disorders such as schizophrenia." (PMID 25189171, 2014). "Interestingly, the expression level of p35, a neuron-specific activator of Cdk5, is decreased in both prefrontal cortex and hippocampus of schizophrenia post-mortem brains." (PMID 24409129, 2013). "Integrating HC ELEs with GWAS and gene regulatory networks further helps pinpoint previously undescribed but functionally relevant genes for BMI (e.g., CDK5, HSD11B1) and schizophrenia (e.g., HYLS1, PMM2)." (PMID 38167462, 2024).
ischemic stroke (15 papers, 2013 to 2025). A stroke disorder caused by obstruction of blood flow to the brain, due to thrombotic (local blood clot formation) or embolic (due to a blood clot or other material traveling from another site) event. "The Cdk5/p25 complex has been implicated in various forms of neuronal injury including ischemic stroke, cortical impact, and blast TBI23,28,50." (PMID 36854738, 2023). "Abundant evidence indicates that CDK5 hyperactivities associated with neuronal apoptosis and death following ischemic stroke." (PMID 28045138, 2017). "CDK1 and CDK5 are associated with detrimental effect on infarct size following ischemic stroke." (PMID 33429982, 2021). "Furthermore, hyperactivity of CDK5, caused by the conversion of the CDK5 activator p35 to p25, has been reported to mediate neuronal death in ischemic stroke." (PMID 31644666, 2019). "There have been various reports including ours, describing functions of Cdk5 in endothelial cells: in detail, endothelial Cdk5 was implicated in endothelial senescence, in neovascularization after ischemic stroke, and in diseases associated with NO dysfunction." (PMID 26755662, 2016). "Thus, CDK5 is activated in ischemic stroke and this activation may be caused by CDK5-Tyr15 phosphorylation and/or p25 accumulation." (PMID 30158515, 2018). "Conditional knockout of Cdk5 confers neuroprotection from cortical impact, ischemic stroke, and mouse models of AD23,28,29." (PMID 36854738, 2023). "In MCAO rats, zinc-induced CDK5-Tyr15 phosphorylation activates CDK5 in the hippocampus, which exacerbates neuronal death in ischemic stroke." (PMID 36671413, 2022). "As a unique Cdk in the nervous system, Cdk5 has been demonstrated to play an important role in the pathological process of ischemic stroke." (PMID 35966199, 2022). "In ischemic stroke in humans, CDK5, p35/p25, and p-CDK5 protein expression were upregulated in infarcted tissue." (PMID 33429982, 2021). "Specific inhibition of either CDK1 or CDK5 showed a beneficial effect on neurological score following ischemic stroke." (PMID 33429982, 2021). "CDK5/p25 hyperactivity was observed in ischemic stroke patients, as well as in several mice and rats models of brain ischemia." (PMID 33429982, 2021). "We next investigated the correlation between hypothermia treatment and IL-1 and CDK5 levels in a rat model of ischemic stroke." (PMID 31644666, 2019). "Therapeutic hypothermia suppresses the abnormal activation of CDK5 in neurons following ischemic stroke, which results in a reduction in NF-κB activity and inhibition of caspase 1, ultimately decreasing the caspase 1-dependent production of IL-1β." (PMID 31644666, 2019). "Since CDK5 is abnormally activated and LPA is elevated after cerebral ischemia, we hypothesized that LPA may be related to CDK5, which may lead to neuronal damage during ischemic stroke." (PMID 35501719, 2022). "Although some of the experimental approaches in this manuscript have limitations, these observations suggest the idea that increased LPA after ischemic stroke promotes abnormal activation of CDK5 and tau phosphorylation, which in turn induces neuronal cell death." (PMID 35501719, 2022). "Given that reducing the level of Cdk5 in astrocytes could protect against brain damage in cerebrovascular diseases, it is believed that Cdk5 has great potential in the treatment of ischemic stroke." (PMID 35966199, 2022). "CDK5 expression is increased after ischemic stroke in endothelial cells." (PMID 33429982, 2021). "Interestingly, previous study has demonstrated that ischemic stroke injury is mediated by aberrant Cdk5 activation." (PMID 31371703, 2019). "However, the level of p-CDK5 was significantly upregulated in the intracerebral ischemic penumbra derived from animals with ischemic stroke compared with that in the penumbra from animals who underwent sham surgery (p<0.05)." (PMID 31644666, 2019). "Our study revealed an increase in CDK5 in animals after ischemic stroke." (PMID 31644666, 2019).
ischemic stroke (continued). "Currently, agents that specifically target CDK5 hyperactivity in ischemic stroke are scarce, but TFP5 has potential to serve as a CDK5-targeting agent and might also be used as an agent in co-treatments for ischemic stroke." (PMID 28045138, 2017). "Therefore, during ischemic stroke, CDK5 may induce activation of the inflammasome, which then leads to neuronal damage." (PMID 31644666, 2019). "Cdk5 inhibition with scCdk5mir astrocytes, Cdk5 RNAi-based therapy or transplanted with PTPN21 also confers neuroprotection in ischemic stroke." (PMID 35966199, 2022). "We synthesized a membrane-permeable peptide that specifically binds to CDK5 with a chaperone-mediated autophagy targeting motif (Tat-CDK5-CTM) and tested its therapeutic effects on a mouse model of ischemic stroke." (PMID 31595208, 2019). "Thus far, strategies to specifically inhibit CDK5 hyperactivity have not been studied in adult ischemic stroke." (PMID 28045138, 2017). "On this base, we propose that p35/cdk5 signalling elicits a specific protective role during in vitro angiogenesis and together with the observed protective action of the CIP peptide, may potentially aid in tissue remodelling after ischaemic stroke." (PMID 24098701, 2013).